CD4 (CD4 molecule)
Diseases named in the same sentence as CD4 in open-access papers (continued):
Sharing a sentence is not in itself a finding about the gene and the disease.
tumor (continued). "Concurrently, there is a marked increase in CD4/CD8+ T cell infiltration and IFN‐γ expression within the tumor tissue, ultimately enhancing the therapeutic efficacy of PD‐1 antibodies by boosting T cell immunity and improving the TME." (PMID 40530896, 2025). "The 5-plex staining showed that all tested cell types - tumor cells (Pan-Cytokeratin; PCK), macrophages (CD68), B-cells (CD20) and cytotoxic T (CD8) and T-helper (CD4) cells - were present in the tested samples." (PMID 40845489, 2025). "We measured the total percentage of immune cells (CD45+) and T-cell subsets (CD4+, CD8+) as well as the number of cells per milligram of tumor." (PMID 41029436, 2025). "In melanoma patients, CD4+ T cells and dendritic cells (particularly CD123+ pDCs) contribute to spontaneous tumor regression." (PMID 40136652, 2025). "The intervention with TNF-α resulted in a significant reduction of CD3+, CD4+, and CD8+ T cell infiltration in the tumor microenvironment, alongside alterations in the tumor compartments." (PMID 40861469, 2025). "In line with this evidence, a significant decrease of immunoactive CD4+ and CD8+ T cells and an increase of immunosuppressive M2 macrophages were observed in IMPC both from bioinformatics analysis and pretreatment tumor samples assessment." (PMID 40821778, 2025). "CD4+ T cells and CD8+ T cells are both important players in T cell-mediated local anti-tumor immune responses." (PMID 41142594, 2025). "In triple-negative breast cancer models, combining PB Lipo–PDT with PD-L1 blockade markedly increased intratumoral CD4+/CD8+ T-cell infiltration and achieved ~79% tumor growth inhibition." (PMID 41149218, 2025). "For example, eosinophils can promote the recruitment of CD4 + and CD8 + T cells into the TME, and the GM-CSF-IRF5 signaling axis in eosinophils can also activate T cell responses to promote anti-tumor immunity." (PMID 40131539, 2025). "LGG-EV modulated intestinal immunity by increasing the CD8+ T/CD4+ T cell ratio in mesenteric lymph nodes and enhancing the ratio of MHC II+ DC cells, CD4+ T cells, and CD8+ T cells in tumor tissues." (PMID 41472171, 2025). "It was found that GP@Gel Nap‐T significantly increased the infiltration of CD4+ T, CD8+ T, and NK cells into tumor tissues and TDLNs, thereby boosting the antitumor immune response." (PMID 39716923, 2025). "Following batch correction and dimensionality reduction, unsupervised clustering identified nine major cell types: B cells, CD4+ T cells, CD8+ T cells, endothelial cells, epithelial (tumor) cells, fibroblasts, macrophages, mast cells, and monocytes." (PMID 41462979, 2025). "MPE had higher proportions of CD45+ immune cells and CD3+ T cells (70.5% vs 50%) compared with tumor and was enriched for effector CD8+ T cells, CCR7C−D45RA− effector memory CD4+ T cells, and quiescent CD25highCD127low regulatory CD4+ T cells." (PMID 41415427, 2025). "Therefore, the enhanced cytokine secretion ability of tumor-infiltrating CD4+ T cells in the treatment group may not be directly caused by L-SeMet but rather indirectly influenced by CD8+ T cells." (PMID 40141154, 2025). "Administered on day 13 of the first three chemotherapy cycles, WOKVAC was found to increase T-bet+ CD4+ and CD8+ tumor-infiltrating lymphocytes (TILs), key markers of type I immune polarization." (PMID 40943636, 2025). "When we quantified the proportions of segmented cells expressing the T cell markers CD4 or CD8, or B cell marker CD20 within histologically defined tumor domains, T cells were found to be ~8-fold more abundant than B cells." (PMID 41000797, 2025). "Systemic administrationof CpG@MSN-PEG/PEI@OMVs effectively suppressed tumor growth and preventedlung metastasis primarily by promoting APC maturation, inducing M1macrophage polarization, and activating IFNγ-secreting CD4+ and CD8+ T lymphocytes." (PMID 40392526, 2025).
tumor (continued). "While our work focuses on the role of NOTCH1 in inducing tumor-intrinsic STING expression and activation, NOTCH1 has been shown to inhibit STING activation in CD4+ T cells via binding to the cyclic dinucleotide binding site." (PMID 40627448, 2025). "In tumor tissues with higher levels of PPT1+ macrophages, the level of CD4+ Tregs shows a mild upward trend, while the infiltration of CD8+ T cells significantly increases." (PMID 41514551, 2025). "We found that 24 h after two rounds of antibody administration, the combination of anti-BTLA and anti-PD-L1 mAbs significantly increased the tumor infiltration of CD8+ and CD4+ T cells compared to that in the other groups." (PMID 40463377, 2025). "First, the CD4+ and CD8+ T lymphocytes were analyzed, as these effector cells mediate anti-tumor cellular immunity." (PMID 41383334, 2025). "In this study, we identified a higher proportion of CXCL13+ CD4+ and CD8+ T cell subsets in pre-treatment tumor tissues, which correlates with recurrence of CSCC." (PMID 40464813, 2025). "For instance, studies have shown that even a small number of CD4+ T cells can eradicate tumors that evade direct CD8+ T cell targeting, with CD4+ effector T cells clustering predominantly at tumor-invasive margins." (PMID 41212769, 2025). "In TNBC samples, the expression of PD-1 and TIM-3 on CD4+ and CD8+ T cells was significantly higher in the tumor tissue compared to the peripheral blood." (PMID 40148963, 2025). "Specifically, we observed increased population of M2 macrophages (CD206+F4/80+) in tumor tissue and spleen, accompanied by a reduced CD8+/CD4+ T cell ratio." (PMID 40963562, 2025). "Tregs are primarily utilized as possible targets for suppressing the activation and differentiation of CD4+ helper T cells and CD8+ cytotoxic T cells, as well as for promoting reactivity to self and tumor-specific antigens." (PMID 40224950, 2025). "Further evaluation of the immune effects of ChS-Ce6-induced pyroptosis showed a significant increase in the proportion of CD80+CD86+ cells in tumor-draining lymph nodes and a markedly higher infiltration of CD4+ and CD8+ T cells in the tumor tissues." (PMID 40698137, 2025). "Flow cytometric analysis of the tumor microenvironment (TME) revealed that F1/F3 increased T cell infiltration, particularly by boosting CD4+ T cell numbers while reducing CD8+ T cells." (PMID 40573908, 2025). "Owing to the potent cytotoxic activity of T cells, previous research predominantly focused on tumor-specific CD8+ T cells, while CD4+ T cells were recognized as helpers for CD8+ T cells." (PMID 40012553, 2025). "Stroma cell labeling indices of CD4**, CD8*, Foxp3*, CD68*, CD163**, and CD11c* were significantly higher in both the tumor core and the invasive front of cSCC samples as compared to BCC (*p < 0.001; **p < 0.050)." (PMID 41068337, 2025). "The B16‐OVA model displayed homogeneous tumour growth, pigmentation and high immune infiltrate (CD8+ T cells p < 0.001; CD4+ T cells p < 0.05, regulatory T cells p < 0.001)." (PMID 40898695, 2025). "Tumors treated with TTFields exhibit increased infiltration of immune cells, including CD45 + cells, CD4+, and CD8 + lymphocytes, creating an immunologically “hot” tumor microenvironment compared to untreated “cold” tumors." (PMID 39881333, 2025). "LGG-EV regulated intestinal immunity by increasing the CD8 + T/CD4 + T cell ratio in mesenteric lymph nodes and enhancing the ratio of MHC II + DC cells, CD4 + T cells, and CD8 + T cells in tumor tissues." (PMID 40549339, 2025). "TTN mutations also inhibit ANKRD1 expression via JUN disruption and enhance CD4/CD8 T‐cell infiltration, improving anti‐tumour immunity and outcomes." (PMID 39748197, 2025). "•HO-1 inhibition combined with docetaxel boosts CD4+ and CD8+ T cells infiltration, enhancing the immune response within tumor tissues." (PMID 40037158, 2025).
tumor (continued). "This study broadens the understanding of how CBD stimulation within the tumor microenvironment modulates CD4+ T cells and CD8+ T cells by facilitating their interactions with both immune and tumor cells." (PMID 40475776, 2025). "OVA + CR108 treatment elicited significant increased tumor-infiltrating CD8+ T cells compared to other groups, while CD4+ T cell infiltration was minimally altered." (PMID 40606756, 2025). "A recent study produced CD4+ CAR T cells in vivo by injecting the AAV-carrying CAR gene, resulting in anti-tumor immunological characteristics and potent efficacy against human T-cell leukemia." (PMID 40821123, 2025). "Immune cell infiltration levels, including CD4, CD8, FOXP3, CD163‐positive cells and expression levels of TGFβ1 and SMAD3 proteins in tumor tissue were evaluated by immunohistochemistry." (PMID 41187938, 2025). "Meanwhile, CD4+ Th cells promote B cell antibody production and CD8+ T cell activation by secreting cytokines, while CD8+ T cells recognize tumor antigens and elicit cytotoxic responses." (PMID 40612858, 2025). "ICIs facilitate an enhanced infiltration of CD4+ and CD8+ T cells in the tumor microenvironment, contributing to an amplified immune response." (PMID 40432892, 2025). "Results of the flow cytometry experiments demonstrated a notable augmentation in the population of CD3+, CD4+ and CD8+ T cells, which successfully activates the immune system and recruits immune cells to attack the tumor." (PMID 40698137, 2025). "Previous studies showed that proliferative CD4+ T cells can drive immune checkpoint blockade (ICB) therapy resistance in ccRCC via TME modulation and tumor cytolysis." (PMID 41332473, 2025). "Effective anti-tumor responses require both CD8+T cells recognizing tumor antigens and activated CD4+T cells within the TME." (PMID 40963596, 2025). "The accumulation of CD4/FOXP3 Treg cells and CD206 M2 macrophages in the tumor, as stained by IF, was significantly lower in the UMSC/miR-124-PD-1 treated group compared to other treatments." (PMID 40134003, 2025). "Thereby, tumor tissue contained significantly lower amounts of CD4+ T cells compared to both liquid samples, whereas the proportion of ascites-derived CD8+ T cells was significantly higher than PB and tumor tissue." (PMID 41221283, 2025). "To delve deeper into the role of NCL in T cells, we established an in situ tumor model and utilized flow cytometry to analyze the quantities of NCL+CD4+ T cells and NCL+CD8+ T cells in both normal lung tissue and tumor tissue." (PMID 40346484, 2025). "Specifically, patients with SCC exhibited higher expression levels of PD-1 on conventional CD4+ T helper cells and CD8+ T cells in both primary tumours and draining lymph nodes, indicating activated but possibly also more exhausted T cells." (PMID 40639721, 2025). "The relationship between FMR1 expression and tumor immune infiltration was analyzed via the TISIDB database, and after co-culture, cytokine secretion by CD4+ T cells was assessed using ELISA following FMR1 knockdown in tumor cells." (PMID 41184982, 2025). "Intratumoral cDC1s obviate the reliance on endogenous DCs and are better able to sensitize both CD4+ and CD8+ T cells to specific tumor antigens." (PMID 40333343, 2025). "These beneficial effects are largely attributed to the presence of CD4+ and CD8+ effector T cells, which mediate anti-tumor activity and correlate with immunotherapy benefit." (PMID 41169398, 2025). "Significant differences in the percentage of these cells were observed in tumor tissue and lungs of aged OVX 4T1 tumor-bearing mice: tacalcitol increased CD3+CD4+ lymphocytes in both tissues, whereas calcitriol increased them only in the lungs." (PMID 40894304, 2025). "CD4+ and CD8+ T-cell infiltration was substantially increased in the combination group, indicating a shift toward a more immunologically active tumor microenvironment." (PMID 41041327, 2025).
tumor (continued). "In iCoup mice, we saw a significant increase in the frequency of tumor-infiltrating T cells, including both CD8+ and CD4 + T cells." (PMID 40796746, 2025). "In the majority of tumor types, SUSD3 expression was positively correlated with the infiltration of B cells, CAFs, dendritic cells, CD4+ T cells, macrophages, CD8+ T cells, monocytes, NK cells, and Treg cells." (PMID 40191190, 2025). "CCR5+CD4+ T cells can increase CD40L/CD40-mediated APC maturation and promote the activation of DCs and CD8+ T cells, thus playing an anti-tumor role." (PMID 40205945, 2025). "CD4+ helper T cells identify peptides on MHC Class II molecules and transmit signals to other immune cells to aid in inhibiting tumor growth." (PMID 40145100, 2025). "DCN as a therapeutic gene promotes the degradation of extracellular matrix (ECM) and attenuates transforming growth factor (TGF)-β-mediated immunosuppression to elevate CD4+ and CD8 T+ cells and simultaneously attenuate Treg accumulation in tumor tissues." (PMID 40335925, 2025). "This process led to Treg cells inhibition and enhanced infiltration of T cells (both CD8+ and CD4+) within tumors, effectively preventing TNBC metastasis via treating both primary tumor and distant tumor growth." (PMID 40689201, 2025). "Multiplex immunohistochemistry analysis of B16F10 tumor tissues revealed extensive infiltration of DCs, CD8+ T cells, and CD4+ T cells in the tumor microenvironment of FL/GM-DC-vaccinated mice." (PMID 40977690, 2025). "In this model, YAP1 upregulation suppressed CXCL16-driven CD4+/CD8+ TIL recruitment and increased MMP7 expression, resulting in elevated RCB scores and reduced tumor remission." (PMID 40731926, 2025). "The LOW group, when compared to the CIMP subset, showed the highest scores for CD3, CD4, CD8, FOXP3 and PD-1 in intra-tumor and extra-tumor compartments." (PMID 40682094, 2025). "We utilized 5 patch/plaque MF skin biopsies (majority from early-stage patients), 8 MF tumor biopsies (all from advanced-stage patients), and 8 healthy control biopsies to evaluate lesion-specific CD5 gene expression on CD4 T cells." (PMID 41226451, 2025). "The findings indicated that GMIP expression in most TCGA tumours was positively correlated with the infiltration levels of B cells, CAF, CD4+ T cells and NKT cells, while it was negatively correlated with the infiltration levels of MDSCs." (PMID 40275529, 2025). "Mechanistically, CD4+ CAR-T cells serve as a main source of IFN-γ, which can act on tumor cells from a distance, selectively inducing apoptosis in tumors sensitive to cytokine-driven cell death, including antigen-negative variants." (PMID 39981247, 2025). "In animal models, LCG CAR-T cells significantly inhibited tumor growth and increased the populations of CD4+CAR-T cells and tumor-infiltrating lymphocytes." (PMID 39981247, 2025). "Compared with controls, mice receiving antiOX40 monotherapy exhibited improved survival; Coadministration of antiOX40 and antiPD-1 led to Treg depletion concurrent with an expansion in CD4+ and CD8+ T cell populations, resulting in complete tumor eradication." (PMID 41561762, 2025). "Increased IL-2 expression shifts the immune response toward tumor attack, allowing NK cells, CD8+ T cells, and CD4+ T cells to infiltrate the tumor microenvironment, while miR-217 downregulates mtKRAS expression." (PMID 41459907, 2025). "SD tumors exhibited substantial CD4+ and CD8+ T cell presence at the tumor periphery, with only CD4+ T cells detected in the core." (PMID 41041061, 2025). "CD4+ naive/central-memory T cells from tdLN directly respond to anti-cytotoxic T lymphocyte antigen-4 (anti-CTLA4) therapy, trafficking via blood to the tumor, where they acquire a Th1 phenotype." (PMID 41030446, 2025).
tumor (continued). "Mature cDC1 cells are the most potent inducers of anticancer immunity as they cross‐present tumor antigens to CD8+ T cells while cDC2 primarily work by presenting exogenous antigens to CD4+ T cells for the initiation of T helper cell differentiation." (PMID 39973474, 2025). "CD4+ central memory T cells exhibited activation phenotypes, including upregulation of CD127 and CCR7, supporting anti-tumor responses by sustaining immune memory and survival signals." (PMID 41194936, 2025). "Immune profiling indicated that normal thyroid tissues adjacent to tumors were enriched with CD3+, CD4+, CD8+, and CD20+ lymphocytes compared with tumor centers." (PMID 40469283, 2025). "Both the co-expression and single expression of CXCR5 or CCR6 in HER2-CAR T cells resulted in a markedly higher positive staining for CD4 + and CD8 + CAR T cells in the tumor tissue compared to those in the HER2-CAR T cell and Control-T treatment groups." (PMID 40764989, 2025). "These vaccines have been associated with elevated IFN-γ secretion, strong activation of CD4+ Th1 and CD8+ CTLs, and suppression of both primary tumor growth and metastatic spread." (PMID 40943636, 2025). "In inflammation models, intestinal epithelial cells promote naïve CD4+ T cell differentiation into Th17 cells, demonstrating how metaplastic cells reshape the immune microenvironment and adopt CRC‐like tumour characteristics." (PMID 40785647, 2025). "Several were most upregulated in specific subsets, such as multi-cytokine in CD8 memory; TIMD4/TIM3 in CD8 CM and γδT; CTLA4/CD38 in Treg, CD4 memory and CD8 CM; and OX40/EBI3 in tumor-infiltrating T cells." (PMID 40903640, 2025). "The IL-1αMPs also triggered the expansion and activation of CD4 + T cells, cytotoxic CD8 + T cells and natural killer (NK) cells in addition to DCs, suggesting the induction of a broad anti-tumor immune response." (PMID 40169985, 2025). "To spatially characterize TIL-B infiltration and interaction with other immune subsets, we compared five TIL-B-poor and six TIL-B-rich OCSCC using an m-fIHC panel optimized for tumor cells, CD163+ macrophages, CD4+, CD8+, and FoxP3+ regulatory T-lymphocytes." (PMID 39796740, 2025). "We also observed an increase in splenic CD3+ T cells, CD4+ T cells, CD8+ T cells, NKTs, and NKs in Tnfrsf14KD‐ID8 tumor‐bearing mice." (PMID 40105652, 2025). "Across prediction models, the top 5% of potentially tumor-reactive CD8 and CD4 T cells occupied clear clusters of predominantly tissue resident/effector memory CD8 T cells and tissue resident memory CD4 T cells, respectively." (PMID 40848148, 2025). "Smoke-exposed mice had a globally attenuated anti-tumor immune response with decreased CD3+ lymphocytes, CD4+ T cells, CD8+ T cells, and CD11c+ MHC II + dendritic cells." (PMID 40104059, 2025). "Previous research has indicated the importance of both CD4+ and CD8+ T cells in mosunetuzumab‐mediated tumor killing." (PMID 41140808, 2025). "Next, we validated the infiltration of CD4+ T cells, CD8+ T cells, and CD19+ B cells upon CBD stimulation by IHC analysis in tumor sections obtained from immune-competent C57BL/6J wild-type mEER mice." (PMID 40475776, 2025). "Pyroptosis adjuvants (PTAVs) produced a strong immune response during tumor treatment with increased proportions of CD3+ T cells, CD8+ T cells, CD8+/CD4+ and DCs, effectively activating cellular immunity." (PMID 40698137, 2025). "Potential predictors of CMV reactivation were: early CD4 + and absolute lymphocyte count after the first cycle of R-BENDA; high tumor burden; and the presence of B symptoms." (PMID 41175237, 2025). "CD4+ and CD8+ T cells induce the upregulation of MHC-I and MHC-II expression on tumor cells and APCs following the recognition of homologous antigens; this can help to enhance our understanding of neoantigen recognition." (PMID 40061134, 2025).